FFAR2 (free fatty acid receptor 2)
Diseases named in the same sentence as FFAR2 in open-access papers (continued):
Sharing a sentence is not in itself a finding about the gene and the disease.
lung adenocarcinoma (5 papers, 2023 to 2026). A carcinoma that arises from the lung and is characterized by the presence of malignant glandular epithelial cells. "Furthermore, FFAR2 is highly expressed in the myeloid-derived suppressor cells (MDSCs) from the tumor of lung adenocarcinoma (LUAD) patients which is greatly associated with poor prognosis." (PMID 38402237, 2024). "And FFAR2 is also highly expressed in human lung adenocarcinoma tumor tissues and tumor-bearing mice splenic MDSCs." (PMID 38402237, 2024). "The findings provide a new strategy for lung adenocarcinoma treatment: FFAR2 agonists (such as propionate) may serve as potential adjuvants to enhance the efficacy of immunotherapy or targeted therapy." (PMID 41003841, 2025). "In lung adenocarcinoma, the final metabolite of FAO, acetic acid, contributes to immune suppression via free fatty acid receptor 2 (FFAR2)." (PMID 39990210, 2025). "Although both FFAR2 and FFAR3 are receptors for SCFAs, only FFAR2 is highly expressed in tumor tissues and positively correlated with poor prognosis of lung adenocarcinoma patients." (PMID 38402237, 2024).
melanoma (5 papers, 2009 to 2024). A malignant, usually aggressive tumor composed of atypical, neoplastic melanocytes. "Loss of FFAR2 (or obstruction of ligand binding) may be a significant marker of melanoma progression, and is already being examined as a therapeutic target for metabolic and inflammatory diseases." (PMID 33108391, 2020).
colon adenoma (4 papers, 2023 to 2024). An adenoma that arises from the colon. "Loss of FFAR2 promotes the development of colon adenoma in ApcMin/+ mice and enhances long-chain fatty acid β-oxidation and bile acid metabolism." (PMID 38590663, 2024). "FFAR2 deficiency was reported to promote the development of colon adenomas and the progression of adenoma to adenocarcinoma and enhanced the downstream cAMP–PKA–CREB–HDAC pathway." (PMID 37287005, 2023). "Literature shows that knocking out (KO) of FFAR2 promoted colon adenoma development in the ApcMin/+/DSS mice and adenocarcinoma progression in the AOM/DSS mice." (PMID 39432182, 2024).
COVID-19 (4 papers, 2021 to 2025). A disease caused by infection with severe acute respiratory syndrome coronavirus 2. "Our investigation explored potential associations between gene expression of AHR, FFAR2, FXR, and TGR5, and COVID-19 outcomes in patients with MAFLD." (PMID 38932276, 2024). "On the other hand, FFAR2 and FFAR4 have been shown to downregulate Th2 inflammatory pathways implicated in cytokine storm in severe COVID-19 cases, including inflammatory cytokines IL-1β and IL-6." (PMID 37515117, 2023). "Interestingly, FFAR2 appears to play a role in regulating probiotic activity, which has been shown to reduce IL-6 levels in COVID-19 patients." (PMID 38932276, 2024). "Similar analysis was performed for FFAR2 gene, which did not however show any significant association with COVID-19 severity." (PMID 34458692, 2021). "In patients with COVID-19 and MAFLD, FFAR2 expression showed positive correlations with segmented neutrophils and bands (immature neutrophils), indicating a potential influence on specific immune cell populations." (PMID 38932276, 2024). "This study investigated the relationships between gene expression of AHR, FFAR2, FXR, and TGR5, and COVID-19 outcomes in patients with MAFLD." (PMID 38932276, 2024). "Taken together, these findings suggest that AHR, FFAR2, FXR, and TGR5 may play significant roles in the progression of both COVID-19 and MAFLD." (PMID 38932276, 2024).
heart failure (4 papers, 2023 to 2025). Inability of the heart to pump blood at an adequate rate to meet tissue metabolic requirements. "Hub genes including LRRK2, BMI1, KBTBD7, and FFAR2 were associated with the risk of heart failure." (PMID 38137330, 2023).
lung carcinoma (4 papers, 2023 to 2025). "We finally examined whether FFAR2 deficiency enhanced lung cancer progression." (PMID 37287005, 2023). "Functionally, treatment with propionate (an agonist of FFAR2) significantly inhibited human lung cancer migration, invasion, and colony formation induced by TLR2 or TLR3 by attenuating the cAMP-AMPK-TAK1 signaling axis for the activation of NF-κB." (PMID 37287005, 2023). "In this study, we demonstrated that FFAR2 was negatively involved in lung cancer progression induced by TLR2 and TLR3 through the suppression of the cAMP-AMPK-TAK1 signaling axis for the activation of NF-κB." (PMID 37287005, 2023). "Collectively, these results suggest that FFAR2 signaling functionally antagonizes lung cancer progression induced by TLR2 or TLR3 via the suppression of the AMPK-TAK1 signaling axis for the activation of NF-κB." (PMID 37287005, 2023). "Above data suggest that FFAR2 deletion or pharmaceutical inhibition could be a new strategy to overcome resistance to PD-1/PD-L1 blockade in lung cancer immunotherapy." (PMID 38402237, 2024). "In addition, the mRNA expression of FFAR2 was greatly increased in urethane-induced mice lung cancer tissues as compared to normal lung tissues." (PMID 38402237, 2024). "We found that FFAR2 was negatively associated with TLR2 and TLR3 in lung cancer." (PMID 37287005, 2023). "Functionally, treatment with propionate (an agonist of FFAR2) significantly inhibited human A549 or H1299 lung cancer migration, invasion, and colony formation induced by TLR2 or TLR3 through the attenuation of the cAMP-AMPK-TAK1 signaling axis for the activation of NF-κB." (PMID 37287005, 2023). "In summary, our study identified negative regulation by propionate, which is an SCFA and recognized by FFAR2, in TLR2- and TLR3-induced lung cancer progression." (PMID 37287005, 2023). "Taken together, these results suggest that FFAR2 antagonizes TLR2- and TLR3-induced lung cancer progression." (PMID 37287005, 2023). "Propionate, an agonist of FFAR2, antagonized TLR2- and TLR3-induced lung cancer migration, invasion, and colony formation by inhibiting the AMPK-TAK1 signaling axis for the activation of NF-κB." (PMID 37287005, 2023). "We next explored the molecular mechanism by which FFAR2 signaling inhibited TLR2- and TLR3-induced lung cancer progression." (PMID 37287005, 2023). "Hub genes including LRRK2, BMI1, MNDA (myeloid cell nuclear differentiation antigen), OTX1, FFAR2, and PITX1 play a significant role in lung cancer progression." (PMID 38137330, 2023). "Collectively, our results strongly suggest the FFAR2 signal might antagonize TLR2- and TLR3-induced lung cancer progression via suppression of the cAMP-AMPK-TAK1 signaling axis for the activation of NF-κB." (PMID 37287005, 2023). "For the functional analysis, we generated FFAR2-knockout (FFAR2KO) A549 and FFAR2KO H1299 human lung cancer cells and performed biochemical mechanistic studies and cancer progression assays, including migration, invasion, and colony-formation assays, in response to TLR stimulation." (PMID 37287005, 2023). "In addition, fatty acid receptor 2 (FFAR2) signaling antagonizes TLR2- and TLR3-induced lung cancer progression by inhibiting the process of cyclic adenosine monophosphate (cAMP)-adenylate-activated protein kinase (AMPK)-transforming growth factor β-activated kinase 1 (TAK1)-NF-κB activation." (PMID 40166469, 2025). "Our results suggest that FFAR2 signaling antagonized TLR2- and TLR3-induced lung cancer progression via the suppression of the cAMP-AMPK-TAK1 signaling axis for the activation of NF-κB, and its agonist might be a potential therapeutic agent for the treatment of lung cancer." (PMID 37287005, 2023). "In contrast, the down-regulation of FFAR2 in lung cancer did not attenuate the cAMP-AMPK-TAK1 signaling axis for the activation of NF-κB, thereby enhancing TLR2- and TLR3-induced lung cancer progression (right)." (PMID 37287005, 2023).
lung carcinoma (continued). "The clinical TCGA data showed a significant down-regulation of FFAR2, but not FFAR1, FFAR3, and FFAR4, in lung cancer, and a negative correlation with TLR2 and TLR3." (PMID 37287005, 2023). "A549 and H1299 lung cancer cells were treated with vehicle, HKLM (an agonist of TLR2), or poly(I:C) (an agonist of TLR3) in the presence or absence of propionate (an agonist of FFAR2), and the cell migration assay was performed." (PMID 37287005, 2023).
colorectal adenocarcinoma (3 papers, 2017 to 2023). The most common type of colorectal carcinoma. "FFAR2 has been reported to have significantly reduced expression in colorectal adenocarcinoma, and propionate, the ligand for FFAR2 and FFAR3, is shown to reduce proliferation and promote apoptosis in several cancer cell types." (PMID 29049318, 2017).
influenza infection (3 papers, 2022 to 2024). "Moreover, pharmacological activation of SCFA receptor FFAR2 aped the acetate effects and imparted protection against post-influenza pathogenic superinfections." (PMID 36275735, 2022). "Supplementation with acetate during influenza infection supported lung defenses against secondary pneumococcal infection in a free fatty acid receptor 2 (FFAR2)-dependent manner, thereby augmenting the lethal outcomes." (PMID 36275735, 2022).
myocardial infarction (3 papers, 2012 to 2025). Gross necrosis of the myocardium, as a result of interruption of the blood supply to the area, as in coronary thrombosis. "Another potential reason for the 5-fold difference is the decrease of FFAR2 in peripheral venous leukocytes of myocardial infarction patients, reported by Ruan J, etc.." (PMID 40308581, 2025). "In human myocardial infarction, the myeloid occupied most FFAR2+ cells, followed by the fibroblast and cardiomyocyte." (PMID 40308581, 2025). "The existence of FFAR2+ and FFAR3+ cells in human myocardial infarction tissue, by immunofluorescent co-staining for FFAR2/3 and canonical marker genes of monocytes and macrophages (CD14, CX3CR1, and CD68), indicating the existence of FFAR2/3 positive monocytes and macrophages." (PMID 40308581, 2025). "Despite the absence of FFAR3+ cells in the sma dataset, which may come from both low proportion and cell capture limitations, the existence of FFAR2+ and FFAR3+ monocytes and macrophages cells in human myocardial infarction tissue has been proved by immunofluorescent co-staining in this study." (PMID 40308581, 2025). "The proportion of FFAR2+ cells and FFAR3+ cells in normal heart hca dataset was much higher than that in the myocardial infarction datasets, which could be explained by the adoption of CD45+ cell enrichment method in hca dataset, leading to more captured myeloid cells." (PMID 40308581, 2025).
steatosis (3 papers, 2021 to 2026). Increased lipid within the cytoplasm of cells. "The consumption of the prebiotic resulted in the transportation of substantial acetate content to the liver via the portal vein, in which the SFCA activates hepatic FFAR2 signalling, thereby likely modulating hepatic insulin signalling to protect against steatosis." (PMID 34530928, 2021).
Alzheimer disease (2 papers, 2023 to 2025). A progressive, neurodegenerative disease characterized by loss of function and death of nerve cells in several areas of the brain leading to loss of cognitive function such as memory and language. "Bicyclo[2.2.1]heptan-2-ol, 1,3,3-trimethyl-(fenchol), a terpene found in various plant oil extracts, has been demonstrated as a potent activator of free fatty acid receptor 2 (FFAR2) signaling, which may prevent the increase in amyloid-beta (Aβ)-stimulated neuronal toxicity in Alzheimer’s disease." (PMID 38140285, 2023).
cervical cancer (2 papers, 2022). A primary or metastatic malignant neoplasm involving the cervix. "For example, SCFAs inhibited proliferation of human cervical cancer HeLa cells via down-regulating free fatty acid receptor 2 (FFAR2) expression." (PMID 36140990, 2022).
Cognitive impairment (2 papers, 2025). Abnormal cognition is characterized by deficits in thinking, reasoning, or remembering. "Acetic acid has been shown to alleviate cognitive impairment in type 1 diabetic mice, and butyrate ameliorates cognitive deficits in AD mouse models via binding to its receptors FFAR2 and FFAR3." (PMID 40236783, 2025).
gastric cancer (2 papers, 2020 to 2025). A primary or metastatic malignant neoplasm involving the stomach. "However, contradictory results were early reported about the FFAR2 expression in gastrointestinal cancer; a first study revealed a higher FFAR2 expression in colorectal and gastric cancers and the overexpression of this receptor in cancer cells potentiated their growth when xenografted in nude mice." (PMID 33113952, 2020).
gestational diabetes (2 papers, 2016 to 2024). Carbohydrate intolerance first diagnosed during pregnancy. "Since gestational diabetes mellitus (GDM) in humans significantly increases the likelihood of adverse effects on the offspring’s metabolic health, we assessed whether the glucose tolerance impairment in the Ffar2-/- mothers impacted the glucose homeostasis of their offspring." (PMID 27959892, 2016).
hypercholesterolaemia (2 papers, 2021 to 2022). "Furthermore, the absence of free fatty acid receptor 2 (FFAR2), an acetate receptor, abolished the protective effect of inulin, as indicated by the more severe liver hypertrophy, hypercholesterolaemia and inflammation." (PMID 34530928, 2021).
lung fibrosis (2 papers, 2024 to 2025). "Increased ILC2 is known to promote collagen deposition, ECM remodeling, fibroblast activation and other processes that promote lung fibrosis, whereas it has been shown that SCFAs can inhibit ILC2 proliferation and inhibit lung fibrosis through FFAR2-independent mechanism." (PMID 38362497, 2024).
multiple sclerosis (2 papers, 2024 to 2025). A progressive autoimmune disorder affecting the central nervous system resulting in demyelination. "The interest in short-chain fatty acids (SCFAs) has grown steadily in recent years due to their clinical relevance in certain diseases such as multiple sclerosis and other inflammatory diseases, but not much is known of FFAR2 and FFAR3 (free fatty acid receptor 2 and 3) in pigs." (PMID 39024309, 2024).
rheumatoid arthritis (2 papers, 2023 to 2025). A chronic, systemic autoimmune disorder characterized by inflammation in the synovial membranes and articular surfaces. "In an experimental model of rheumatoid arthritis (RA), free fatty acid receptor 2 (FFA2) on CD19+ B cells underlay the protective effects." (PMID 36982235, 2023).
type 1 diabetes (2 papers, 2020 to 2023). "Our data revealed that butyric acid can mediate Ffar2 to increase blood insulin in STZ-induced type 1 diabetic mice." (PMID 32404878, 2020). "Future work is required to determine if GLP-1 mediates the Ffar2-butyric acid induced insulin secretion in the STZ-induced type 1 diabetic mouse model." (PMID 32404878, 2020). "A butyrate-enriched diet could partially protect Ffar2 KO mice in a non-obese diabetic background from type 1 diabetic islet inflammation." (PMID 32404878, 2020).
uveitis (2 papers, 2023 to 2025). An inflammatory process affecting a part of or the entire uvea. "Notably, pectin supplementation can upregulate the expression of the SCFA receptor FFAR2/GPR43 in the ileum during the peak phase of uveitis." (PMID 40799652, 2025).
abscess (1 paper, 2018). An inflammatory process characterized by the accumulation of pus within a newly formed tissue cavity which is the result of a bacterial, fungal, or parasitic infection or the presence of a foreign body. "GO analysis with the unique differential promoters involved in Munro’s abscess formation revealed neutrophil and leukocyte chemotaxis as the highest enriched biological processes which include genes like HRH1, PDE4D, CCL25, AIF1, ADAM10, FFAR2, IL1B and TREM1." (PMID 30092825, 2018).
acne (1 paper, 2016). An inflammatory process of the sebaceous glands which is characterized by comedones, nodules, papules and/or pustules on the skin. "The expression of Ffar1 and Ffar2 in acne lesions is not yet quantified." (PMID 27834859, 2016).
Arrhythmia (1 paper, 2024). Any cardiac rhythm other than the normal sinus rhythm. "We confirmed sodium acetate (C2) and sodium butyrate (C4) protect from C. sakazakii-induced arrhythmia, and C2 and C4 protected from septic arrhythmia by activating free fatty acid receptor 2 and 3 (FFAR2 and FFAR3) in mice." (PMID 39228788, 2024).
brain injury (1 paper, 2023). Acute and chronic (see also brain INJURIES, CHRONIC) injuries to the brain, including the cerebral hemispheres, CEREBELLUM, and brain STEM. "Additional studies are needed to determine the role of the gut microbiota-valeric acid-FFAR2-IL-17 pathway in ischemic brain injury in female animals." (PMID 37697393, 2023).
brain ischemia (1 paper, 2023). Diminished or absent blood supply to the brain caused by obstruction (thrombosis or embolism) of an artery resulting in neurologic damage. "Inhibiting FFAR2 may be an intervention for improving the outcome after brain ischemia in old population." (PMID 37697393, 2023).
clostridium difficile infection (1 paper, 2024). Symptomatic infection due to the spore-forming bacterium clostridium difficile. "Similarly, it has also been shown that Ffar2-mediated potentiation of ILC3 activity to produce IL-22 was beneficial to ameliorating Clostridium difficile infection." (PMID 38238790, 2024).
esophageal adenocarcinoma (1 paper, 2021). A malignant tumor with glandular differentiation arising predominantly from Barrett mucosa in the lower third of the esophagus. "The combination of SLC26A9 with AP002478.1, BHLHA15, FFAR2, IGFBP1, KCTD8, and PHYHD1 was also identified as a gene signature for personalized prognosis prediction and targeted therapy of esophageal adenocarcinoma." (PMID 35008199, 2021).
experimental autoimmune encephalomyelitis (1 paper, 2025). An autoimmune demyelinating disease of the central nervous system that is produced experimentally in animals by the injection of homogenized brain or spinal cord in Freund's adjuvant. "DA rats immunized with spinal cord homogenate (SCH) develop experimental autoimmune encephalomyelitis (EAE) which is ameliorated by the treatment of rats with the FFAR2 agonist Cpd1 in the inductive phase of the disease." (PMID 40021945, 2025). "We have recently reported that oral administration of the free fatty acid receptor 2 (FFAR2) agonist Cpd1 in the inductive phase of experimental autoimmune encephalomyelitis (EAE) in rats ameliorates the disease by stimulating the regulatory immune response in the intestine." (PMID 40021945, 2025).
Granuloma (1 paper, 2025). A compact, organized collection of mature mononuclear phagocytes, which may be but is not necessarily accompanied by accessory features such as necrosis. "A diverse array of innate immune cells, including mast cells (MC) (cluster 20: HDC, CPA3, KIT), dendritic cells (DC) (cluster 23: CLNK, WDFY4, FLT3), neutrophils (FCGR3B, FFAR2, CSF3R), and macrophages (CD68, CD163, C1QA/B/C), was also present in these granulomas." (PMID 40772762, 2025).
Hyperinsulinemia (1 paper, 2016). An increased concentration of insulin in the blood. "Unlike the liver specific insulin receptor knockout (LIRKO) mouse used in the previous study, our Ffar2-/- mice do not exhibit elevated plasma insulin concentrations suggesting possibly that maternal hyperinsulinemia may be driving the early-age metabolic impacts in the offspring." (PMID 27959892, 2016).
infarction (1 paper, 2025). A localised pathological necrosis of tissue resulting from obstruction of the blood supply usually by a thrombus, an embolus, or vascular torsion. "There is a 5-fold difference between the proportion of FFAR2+ cells in the normal and infarction human heart dataset (0.21% vs 0.04%)." (PMID 40308581, 2025). "Our analysis highlights the FFAR2 and FFAR3 distribution in different cardiac tissue, cell types, and infarction areas, uncovering the potential effect and mechanisms of SCFAs via FFAR2 and FFAR3 in the heart, and provides a valuable reference for future studies." (PMID 40308581, 2025).